YBX1 (Y-box binding protein 1)
Diseases named in the same sentence as YBX1 in open-access papers (continued):
Sharing a sentence is not in itself a finding about the gene and the disease.
multiple myeloma (16 papers, 2008 to 2025). "Notably, expression of YBX1 was associated with downregulation of immune activation signaling in myeloma and reduced immune cells infiltration, thereby contributed to poor prognosis." (PMID 36717896, 2023). "It is worth noting that inhibiting YBX1 through knockdown has been observed to reduce the levels of Cyclin D1 protein in multiple myeloma cells." (PMID 38255791, 2024). "When co-cocultured with RPMI-8226 myeloma cells with YBX1 knockdown, the frequencies of IFN-γ+ and GZMB+ cells among CD8+ T cells were significantly higher than those in CD8+ T cells co-cultured with control RPMI-8226 cells." (PMID 36717896, 2023). "To validate the findings from our scRNA-seq data regarding YBX1 function in MM, we further performed in vitro experiments on human myeloma cell lines (HMCLs) and primary myeloma samples." (PMID 36717896, 2023). "It has also been shown that down-regulation of YBX1 results in reduced proliferation and increased apoptosis in myeloma cells." (PMID 34753494, 2021). "We further examined the myeloma-T interactions with YBX1 knockdown." (PMID 36717896, 2023). "Together, these results recapitulated and validated the gene expression patterns observed in our scRNA-seq analysis, and suggested that YBX1 facilitated its impacts on myeloma survival and drug response by affecting T cells function and promoting immune suppression." (PMID 36717896, 2023). "Our data suggested YBX1 may contribute to myeloma cells proliferation, as well as immune modulation, which indicate potential roles of YBX1 in regulating both tumor-intrinsic programs and microenvironment remodeling." (PMID 36717896, 2023). "On the contrary, the frequency of TIM3+ CD8+ T cells showed a significant decrease after knocking down YBX1 in myeloma cells, which was consistent with the decreased expression of LGALS9 in RPMI-8226 with YBX1 knockdown, whereas other exhausted markers remained unchanged." (PMID 36717896, 2023). "Consistently, reduced cell viability was found in primary myeloma cells after YBX1 suppression." (PMID 36717896, 2023). "Notably, a feed-forward loop between YBX1 and Myc is essential for multiple myeloma cell survival." (PMID 29029484, 2017). "Through co-culture of T cells and myeloma cells from RPMI-8226 cell line, we found that tumor-binding T cells were increased after YBX1 knockdown in RPMI-8226, which indicated enhanced myeloma-T cells interaction when reducing YBX1 expression." (PMID 36717896, 2023). "After the knockdown of YBX1, cell proliferation was significantly decreased in U266, OPM2 and RPMI-8226 myeloma cell lines." (PMID 36717896, 2023). "Similarly, genetic deletion of Ybx1 in the MOPC315.BM myeloma cell line did not alter proliferation rates." (PMID 41000393, 2025).
osteosarcoma (16 papers, 2011 to 2025). A usually aggressive malignant bone-forming mesenchymal neoplasm, predominantly affecting adolescents and young adults. "Previous studies have reported that dysregulated YBX1 is associated with chordoma, osteosarcoma, synovial sarcoma, and other bone diseases." (PMID 34218256, 2021). "Previous studies have indicated that YBX1 promotes the translation of HIF1α protein by directly binding to the 5’ UTR of HIF1α mRNA to mediate the metastasis of osteosarcoma." (PMID 35692750, 2022). "In addition, overexpression of YBX1 was reported to enhance the metastatic potential of osteosarcoma cells by inducing EMT and migration." (PMID 31481087, 2019). "In osteosarcoma, VEGF165 promotes tumor progression, while VEGF165b opposes it; YBX1, a critical splicing factor, upregulates VEGF165 but downregulates VEGF165b, impacting both their levels and the disease course." (PMID 38255791, 2024). "Therefore, targeting YBX1 may lead to a multi-pronged interference with osteosarcoma biology." (PMID 38561347, 2024). "In osteosarcoma, decreased NSUN6 expression reduced m5C modifications on PEX1 and PEX3 mRNA, leading to PEX1 and PEX3 instability by losing the binding of the m5C recognition protein YBX1." (PMID 41462962, 2025). "Targeting YBX1 may modulate VEGF165 and VEGF165b concurrently, offering a potential avenue for therapeutic intervention in osteosarcoma." (PMID 38255791, 2024).
renal cell carcinoma (16 papers, 2018 to 2026). "CD4+ T cells in renal cell carcinoma stimulate cancer cell proliferation by activating the YBX1/HIF2α signaling pathway." (PMID 40799245, 2025). "Interactions between C1QBP and YBX1 result in decreased C1QBP levels, enhancing YBX1 phosphorylation and nuclear translocation in renal cell carcinoma." (PMID 40799245, 2025). "C1QBP regulates YBX1 and suppresses androgen receptor (AR)-enhanced invasion of renal cell carcinoma cells." (PMID 40799245, 2025). "Cui and colleagues found that YBX1 can interact with Kindlin-2 to repress ROS generation in renal cell carcinoma." (PMID 38965605, 2024). "A previous study has reported that YBX1 plays a profound role in inhibiting ROS generation by interacting with Kindlin-2 in renal cell carcinoma." (PMID 38965605, 2024). "Furthermore, YBX1 promotes the translation of TGFβ1 mRNA in proximal tubule cells, and knocking down YBX1 reduces the downstream signaling molecules of TGFβ1 in renal cell carcinoma." (PMID 38255791, 2024). "In summary, these findings indicate that NNT-AS1 promotes ccRCC progression via the miR-137/YBX-1 pathway, which may provide a promising therapeutic target for renal cell carcinoma." (PMID 34643163, 2021). "Moreover, a study has reported that the YBX1/G3BP1 complex could activate the downstream NF-κB signaling pathway in renal cell carcinoma cells." (PMID 41513625, 2026). "In renal cell carcinoma (RCC), higher expression levels of Y-box-binding protein 1 (YBX1) and lower expression of gC1qR were found in tumor tissues." (PMID 36776869, 2023). "Our previous research has demonstrated that YBX1 interacts with G3BP1 to upregulate its downstream protein SPP1 expression, thereby activating the NF-κB signaling pathway and thus promoting renal cell carcinoma (RCC) metastasis." (PMID 36330442, 2022). "In addition, the complex composed of YBX1 and G3BP1 plays a crucial role in enhancing NF-κB promoter activity and promoting the metastasis of renal cell carcinoma." (PMID 41513625, 2026). "Similarly, another study showed increased YBX1 expression in 32 renal cell carcinoma (RCC) patients, and the genetic ablation of YBX1 in vitro was shown to inhibit the phosphorylation of NF-κB on S536." (PMID 33375283, 2020).
intrahepatic cholangiocarcinoma (14 papers, 2021 to 2025). A carcinoma that arises from the intrahepatic bile duct epithelium in any site of the intrahepatic biliary tree. "In our previous study, circACTN4 promoted intrahepatic cholangiocarcinoma proliferation and metastasis by acting as a molecular sponge of miR-424-5p and interacting with YBX1 to transcriptionally activate FZD7." (PMID 36028854, 2022). "Louis and Coulouarn54 have found that circACTN4 upregulates YAP1 expression by sponging miR-424-5p, and recruits Y-box binding protein 1 (YBX1), thus initiating FZD7 transcription and promoting intrahepatic cholangiocarcinoma progression." (PMID 36861443, 2023). "CircACTN4 can recruit YBX1 to the promoter of FZD7 and activate its transcription in human intrahepatic cholangiocarcinoma cells." (PMID 37907737, 2023). "CircACTN4 has been demonstrated to interact with YBX1 to activate FZD7 transcription, thereby promoting intrahepatic cholangiocarcinoma progression." (PMID 36895010, 2023). "For instance, CircACTN4 was demonstrated to be upregulated in ICC (intrahepatic cholangiocarcinoma) patients, acting as a molecular sponge of miR-424-5p and interacting with YBX1, to transcriptionally activate FZD7, thereby promoting proliferation and metastasis of ICC." (PMID 36304901, 2022). "CircACTN4 promotes intrahepatic cholangiocarcinoma proliferation and metastasis by acting as a sponge for miR-424-5p and by interacting with YBX1 to transcriptionally activate FZD7, which is upregulated in intrahepatic cholangiocarcinoma expression." (PMID 36506086, 2022). "Similarly, circACTN4 facilitates Y-box binding protein 1 (YBX1) recruitment to activate FZD7 transcription and then activates the Wnt and Hippo signalling pathways, thereby promoting intrahepatic cholangiocarcinoma (ICC) growth and metastasis." (PMID 40296024, 2025). "Another study indicated that circACTN4 is upregulated in intrahepatic cholangiocarcinoma by acting as a molecular sponge for miR-424-5p and interacting with YBX1 to transcriptionally activate FZD7, thereby promoting the proliferation and metastasis of intrahepatic cholangiocarcinoma." (PMID 36505874, 2022). "Circ-ACTN4 binds YBX1 and stimulates FZD7 transcription, which in turn promotes intrahepatic cholangiocarcinoma (ICC) proliferation and metastasis, leading to malignant tumor growth and metastasis." (PMID 35116058, 2021).
clear cell renal cell carcinoma (13 papers, 2018 to 2026). "SNHG6 enhances YBX1-mediated HIF1α translation, promoting clear cell renal cell carcinoma carcinogenesis." (PMID 40799245, 2025). "In another study, lncRNA MILIP was shown to bind YBX1, affecting Snail translation and promoting renal clear cell carcinoma metastasis." (PMID 40234937, 2025). "The lncRNA MILIP bound with YBX1 to increase the translation of Snail, leading to the enhanced metastasis of clear cell renal cell carcinoma cells." (PMID 38491348, 2024). "LncRNA SNHG6 promotes carcinogenesis by enhancing the translation of YBX1-mediated HIF1α in clear cell renal cell carcinoma." (PMID 35692750, 2022). "In clear cell Renal Cell Carcinoma (ccRCC), Y-box binding protein 1 (YB1) mediated upregulation of EphA2 by reducing its proteasomal degradation and this strongly correlated with resistance to sunitinib and acquisition of invasive properties." (PMID 33572284, 2021). "Overexpression of SNHG6 was found to promote cell proliferation and metastasis in clear cell renal cell carcinoma (ccRCC) by interacting with YBX1." (PMID 34290738, 2021).
acute myeloid leukemia (12 papers, 2021 to 2025). Acute myeloid leukemia (AML) is a group of neoplasms arising from precursor cells committed to the myeloid cell-line differentiation. "In acute myeloid leukemia (AML), YBX1 serves as a disease-sustaining mediator of jak2-mutated myeloproliferative neoplasms, enhancing the translational capacity of oncogenic transcripts (including MYC) by recruiting polysome chains, thereby driving the survival and proliferation of AML cells." (PMID 40799245, 2025). "In acute myeloid leukemia patients, increased YBX1 expression correlates with adverse genomic abnormalities, indicating its relevance to disease pathogenesis." (PMID 40799245, 2025). "In contrast, YBX1 promotes mRNA decay of MYC in an m6A-dependent manner to maintain the viability of acute myeloid leukemia cells." (PMID 37345125, 2023). "For example, similar to LncRNA, GAS6-AS1 directly binds to YBX1 and inhibits cellular propagation, and leads to acute myeloid leukemia (AML)." (PMID 37253771, 2023). "Here, we aim to assess the functional relevance and mechanistic role of cold shock proteins, and specifically YBX1, in acute myeloid leukemia (AML) in vitro and in vivo." (PMID 34465866, 2022). "In this context, YBX1 forms ribonucleoprotein complexes with IGF2BPs on m6A -modified transcripts, stabilizing key oncogenic mRNAs such as MYC and BCL2 in acute myeloid leukemia (AML)." (PMID 41346602, 2025). "GAS6-AS1 is overexpressed in acute myeloid leukemia (AML) and promotes the progression of AML through the YBX1/MYC axis." (PMID 35962353, 2022). "Preclinically, administration of lentivirus-mediated short hairpin RNA (shRNA) targeting GAS6-AS1 considerably suppresses acute myeloid leukemia cell propagation and disease progression, indicating the crucial roles of GAS6-AS1/YBX1/MYC axis in leukemia." (PMID 34753494, 2021). "IGF2BP2 and IGF2BP3 augmented the stability of DDX21 mRNA in an m6A-dependent manner, followed by recruitment of transcription factor YBX1 by DDX21 on ULK1 gene promoter and elevated transcription of ULK1, which facilitates progression of acute myeloid leukemia." (PMID 39866844, 2025). "In acute myeloid leukemia (AML), DDX21 recruits YBX1 to cooperatively trigger ULK1 expression and promote AML progression." (PMID 40301349, 2025).
breast tumor (12 papers, 2007 to 2024). "To further evaluate the molecular function of YBX1 in promoting breast tumor progression, we analyzed associations between YBX1 and EMT genes." (PMID 34440660, 2021). "Recently, Y-box binding protein-1 (YB-1) was reported as a stronger predictor, of all breast tumor subtypes specific survival, than estrogen receptor or HER-2." (PMID 20649952, 2010).
leukemia (12 papers, 2018 to 2025). A malignant (clonal) hematologic disorder, involving hematopoietic stem cells and characterized by the presence of primitive or atypical myeloid or lymphoid cells in the bone marrow and the blood. "Our results confirmed that the YBX1 protein associated with leukaemia sEVs is indeed located inside the vesicles." (PMID 38499475, 2024). "Next, leukaemia sEVs were incubated with Proteinase K and subsequently lysed with Triton X following protease inhibitor treatment to reveal whether YBX1 is associated with the outer EV membrane or located inside the vesicles." (PMID 38499475, 2024). "Here, inactivation of YBX1 confirms its role as an essential driver of leukemia development and maintenance." (PMID 34465866, 2022). "Of note, the frequency of leukemic stem cells was not significantly decreased in the primary recipient hosts transplanted with Ybx1−/− leukemia cells compared to WT controls." (PMID 34465866, 2022). "A recent report published by Feng and colleagues complements our findings by providing novel insights into how YBX1 binds its target mRNAs in leukemia cells." (PMID 34465866, 2022). "Inactivation of Ybx1 by pIpC injections after engraftment of leukemic cells in primary recipient mice resulted in a delay of leukemia onset and prolongation of survival (median survival of MA9-Ybx1 + /+ 73 days; MA9-Ybx1−/− 91.5 days; p = 0.0121*)." (PMID 34465866, 2022). "To confirm the role of Ybx1 in leukemia maintenance, we used a conditional knockout mouse model that was recently published by our group and allows for conditional deletion of Ybx1 after leukemia onset." (PMID 34465866, 2022). "Even though the cold shock domain as a common structural component of the CSPs is conserved among the family members, only YBX1 showed a potent phenotype in leukemia as well as in other cancers." (PMID 34465866, 2022). "MYC is an attractive target for leukemia therapeutics due to its regulation by multiple signaling cascades, while the co-operator YBX-1 and its regulation of MYC activation is not well understood." (PMID 34753494, 2021). "GAS6-AS1 promote the cooperation of YBX1 with MYC, leading to upregulation of downstream target genes associated leukemia progression, including IL1R1, SRC and RAB27B." (PMID 34753494, 2021). "We revealed that GAS6-AS1 directly binds Y-box binding protein 1 (YBX1) to facilitate its interaction with MYC, leading to MYC transactivation and upregulation of IL1R1, RAB27B and other MYC target genes associated with leukemia progression." (PMID 34753494, 2021). "Additionally, USP47 promotes AML cell proliferation, enhances resistance to imatinib, and eliminates leukemia progenitor cells in CML by stabilizing Y-box-binding protein 1 (YBX1), a vital regulator of cell survival observed in multiple solid tumors and CML." (PMID 39048945, 2024). "P22077, a dual inhibitor of USP7/USP47, overcomes tyrosine kinase inhibitor resistance and eradicates leukemia stem/progenitor cells in chronic myelogenous leukemia through inhibiting its novel substrate Y-box binding protein 1 (YB-1) deubiquitination and suppresses DNA damage repair." (PMID 35301297, 2022). "Thus, the findings reveal that YBX1 is a key factor in leukemia survival, which may provide a research basis for determining whether YBX1 is a therapeutic target for AML." (PMID 35053496, 2022). "In leukemia, GAS6 AS1 binds directly to YBX1, promoting its interaction with MYC and resulting in the activation of MYC target genes associated with leukemia progression." (PMID 40799245, 2025). "Our results show that YBX1 bound to GAS6-AS1, and leukemia promoting functions of GAS6-AS1 were mediated, at least partly, through interacting with YBX1 in AML cells." (PMID 34753494, 2021). "To validate the functional impact of YBX1 depletion in human AML in vivo, we performed a CRISPR-Cas9 mediated knockout as well as shRNA-mediated knockdown of YBX1 in MOLM13 cells and assessed leukemia dynamics after transplantation in humanized mice." (PMID 34465866, 2022).
leukemia (continued). "In contrast, in Ybx1−/− mice sacrificed without clinical signs of leukemia at day 150, no relevant leukemic organ infiltration could be observed." (PMID 34465866, 2022). "In secondary recipient hosts, Ybx1−/− leukemias showed reduced proliferation, failed to re-establish leukemia in 3/10 recipients and significantly prolonged survival compared to Ybx1 + /+ controls (median survival of MA9-Ybx1 + /+ 76 days; MA9-Ybx1−/− 94 days; p = 0.0013**)." (PMID 34465866, 2022). "Likewise, secondary recipients of Ybx1 + /− cells showed prolonged survival (median survival of MA9-Ybx1 + /+ 37 days; MA9-Ybx1 + /− 90 days; p = 0.0042**) and 3/8 (37.5%) of animals failed to establish leukemia within 150 days." (PMID 34465866, 2022).
urothelial carcinoma of the bladder (12 papers, 2017 to 2023). "NSUN2 and YBX1 drive the pathogenesis of urothelial carcinoma of the bladder by targeting the m5C methylation site in the 3′-untranslated region of HDGF." (PMID 37398932, 2023). "The Y box binding protein 1 (YBX1)-mediated m5C modification promoted mRNA stability, which activated oncogenesis of urothelial carcinoma of the bladder." (PMID 34888238, 2021). "NSUN2 and its reading protein Y-box binding protein 1 (YBX-1) are highly expressed in human urothelial carcinoma of the bladder (UCB) and act as oncogenes in an m5C-dependent manner, promoting the development of UCB by increasing the mRNA stability of heparin-binding growth factor (HDGF)." (PMID 35574373, 2022). "The Y-box binding protein 1 (YBX1) is another recently identified m5C reader protein, which was reported to promote the pathogenesis of human urothelial carcinoma of the bladder in an m5C-modification-dependent mechanism, where the binding of YBX1 maintained the stability of target mRNAs." (PMID 31891622, 2019). "It was reported that NSUN2 could cooperate with Y-box-binding protein 1 (YBX1), an m5C ‘reader’, to drive pathogenesis of human urothelial carcinoma of the bladder (UCB) by stabilizing oncogenic mRNAs, such as heparin-binding growth factor (HDGF), via m5C methylation." (PMID 37612540, 2023). "Furthermore, YBX1 could recognize about 60% of m5C mRNAs in urothelial bladder cancer (UCB)-derived T24 cells." (PMID 35365216, 2022). "A recent study showed that in human urothelial carcinoma of the bladder (UBC), NSUN2-mediated m5C modification stabilizes oncogene RNA through the “reader” YBX1, and hypermethylated m5C levels correlate with oncogene mRNA overexpression in UBC cells." (PMID 32978516, 2020). "Moreover, upregulated NUSN2, YBX1, and HDGF expression levels predicted a poorer survival rate in patients with urothelial carcinoma of the bladder." (PMID 35365216, 2022). "In urothelial carcinoma of the bladder, NSUN2 targets the 3' untranslated region (3'-UTR) and stabilizes the mRNA of HGDF by generating the RNA m5C modification, while the reader YBX1 binds to the m5C region with the help of the partner protein ELAVL1 (an mRNA stability maintainer)." (PMID 34512153, 2021).